PKD1 (polycystin 1, transient receptor potential channel interacting)
Diseases named in the same sentence as PKD1 in open-access papers (continued):
Sharing a sentence is not in itself a finding about the gene and the disease.
polycystic kidney disease (continued). "Molecular analysis for polycystic kidney disease revealed a variant of uncertain significance (VUS) in the PKD1 gene." (PMID 36406818, 2022). "PKD1 is associated with polycystic kidney disease, some clinical forms of which present with hearing impairment, although to our knowledge auditory sensitivity has not been tested in the PKD1 knockout mouse." (PMID 36361815, 2022). "Some TSC2 missense mutations (i.e., p.Arg905Gln and p.Gln1503Pro); however, not all missense mutations are associated with milder disease phenotypes, and TSC2/PKD1 contiguous gene deletion is associated with polycystic kidney disease." (PMID 36232477, 2022). "PKD1 encodes a member of the polycystic protein family and is considered associated with polycystic kidney disease." (PMID 35337339, 2022). "ADPKD is mainly caused by mutations of polycystic kidney disease 1 (PKD1) and polycystic kidney disease 2 (PKD2), which encode for polcystin‐1 (PC‐1) and polycystin‐2 (PC‐2), respectively." (PMID 36540879, 2022). "Mutations of the PKD1 gene are involved in polycystic kidney disease, but the role of polycystins as mechanosensor molecules still needs to be clarified." (PMID 35768415, 2022). "In terms of ADPKD, comparison of gene expression profiles in kidney tissues of Pkd1-deficient versus wild-type mice identified 204 genes that were differently expressed in late-stage polycystic kidneys including Arg1." (PMID 33758231, 2021). "The mutations in PKD2 (located at 4q22.1 chromosome), found in the residual 15% of PKD patients, lead to milder kidney polycystic disease symptoms compared with patients with PKD1 mutations." (PMID 32276433, 2020). "Genes PKD1 and PKD2 encode polycystin 1 (PC1) and polycystin 2 (PC2), respectively, that are responsible for ADPKD; yet, the biological function of polycystins remains elusive and controversial." (PMID 33013483, 2020). "ADPKD is genetically heterogeneous and results from mutations in at least two genes, Polycystic Kidney Disease-1 (PKD1) or PKD-2." (PMID 31907669, 2020). "Previously, it has been reported that PKD1 mutation is one of the main genes that cause polycystic kidney disease in patients." (PMID 33200202, 2020). "The other renal features reported at baseline were multiple renal cysts (24.6%), polycystic kidney disease (proven TSC2/PKD1 mutation; 3.4%), renal malignancy (1.4%), and impaired renal function (non-angiomyolipoma-related; 1.9%)." (PMID 33041968, 2020). "Generally, the mutations of the Pkd1 gene are associated with the occurrence of primary cilia‐related polycystic kidney disease, and mice with Pkd1 mutations can exhibit endochondral ossification disorders in the embryonic stage." (PMID 32034931, 2020). "The Consortium of Radiologic Imaging Studies of the Polycystic Kidney Disease (CRISP) cohort revealed that 89.1% had either a PKD1 or PKD2 mutation." (PMID 31488014, 2019). "In fact, the cysts that characterize polycystic kidney disease have been observed in kidney organoids derived from human pluripotent stem cells with CRISPR-Cas9-mutated PKD1 or PKD2 genes." (PMID 30379927, 2018). "Recent reports have suggested a role of PKD1 not only in renal tubular function and structure but rare mutations in this gene as the main also cause underlying polycystic kidney disease, highlighting its importance in kidney complications." (PMID 29695241, 2018). "These diseases result from primary cilia dysfunction, similarly to the polycystic kidney disease caused by a mutation in the PKD1 gene." (PMID 27233669, 2016). "In a single step, our approach allows specific mutation analysis of all genes known for cystic and polycystic kidney disease including the complete PKD1 locus as well as the detection of CNVs in these genes." (PMID 25646624, 2015). "Three of these mutations (37.5 %) were deletions disrupting not only TSC2 gene but also adjacent PKD1 gene, causing polycystic kidney disease in these patients." (PMID 25227171, 2014).
polycystic kidney disease (continued). "Approximately 85% of cases are due to mutation in the polycystic kidney disease 1 gene (PKD1) in chromosome 16 and 15% to polycystic kidney disease 2 gene (PKD2) in chromosome 4." (PMID 23304619, 2012). "Pkd1 mutations in mouse models also cause abnormalities of the skeleton and human subjects with polycystic kidney disease appear to have earlier elevation of the bone-derived hormone FGF23." (PMID 23029375, 2012). "It should be noted that none of the animal models that were shown to be sensitive to rapamycin develop polycystic kidney disease due to mutations in either Pkd1 or Pkd2." (PMID 19863783, 2009). "Polycystic kidney disease is caused by mutations in either PKD1 or PKD2." (PMID 39982357, 2025). "In addition, the proximity of the TSC2 gene to the PKD1 gene, mutations of which cause polycystic kidney disease (PKD), results in a contiguous gene syndrome (CGS)." (PMID 41227201, 2025). "ADPKD is primarily caused by mutations in the polycystic kidney disease genes 1 or 2 (PKD1 or PKD2), and less commonly by variants in other genes such as glucosidase II alpha subunit (GANAB), which have been associated with milder renal phenotypes and concurrent polycystic liver disease." (PMID 41181723, 2025). "PKD1 is associated with polycystic kidney disease, a syndromic CHD37." (PMID 39567769, 2024). "Most of them (10 variants) were in PKD1, the main responsible gene for polycystic kidney." (PMID 38012624, 2023). "Finally, a fetus with polycystic kidney disease carried two missense variants in PKD1 (NM_001009944.2: c.11872G>C, p.(Ala3958Pro); SCV001519082, paternal and c.9499A>T, p.(Ile3167Phe); VCV000440135, maternal) in a compound heterozygous state." (PMID 34974531, 2022). "In patient 26, a female presenting with polycystic kidney disease and noncompaction cardiomyopathy, WES revealed pathogenic variants in PKD1 (p.Cys3081Arg) (Polycystic kidney disease 1, MIM: 173900) and TTN (p.Trp16598Ter) (Cardiomyopathy, dilated, 1G, MIM: 604145)." (PMID 35606766, 2022). "Heterozygous mutation of PKHD1 and PKD1 was detected in two adults with polycystic kidneys." (PMID 32382272, 2020). "The GAIN domain with the GPS motif therefore represents the key structural element with fundamental importance for PC1 and might be polycystic kidney disease’s (PKD) Achilles’ heel in a large spectrum of PKD1 missense mutations." (PMID 26805887, 2016). "The Mayo/Polycystic Kidney Disease Foundation variant database, a research tool, is the best current database of PKD1 and PKD2 variants containing over 2300 variants identified in individuals with polycystic kidney disease, but novel variants are often identified." (PMID 37962562, 2024). "A significant proportion of these cases belong to the ciliopathies macro-category and specifically to polycystic kidney disease, posing the question whether additional variants within PKD1 gene may have a clinical impact, leading to an earlier diagnosis (manuscript in preparation)." (PMID 36782285, 2023). "Finally, several studies reported the potential of ciliary genes as diagnostic and prognostic markers of polycystic kidney disease (PKD1) and diverse disorders such as psoriatic arthritis (NUP62), non-small cell lung cancer (TUBB3) or acute kidney injury (CLUAP1)." (PMID 32276433, 2020). "On the genetic front, hundreds of gene variants can cause or drive the progression of CKD, such as variations in the PKD1 and PKD2 genes in patients with polycystic kidney disease, and COL4A5 gene variants in those with Alport syndrome." (PMID 41598767, 2026). "In Family 10 (P18–P19) and Family 11 (P20), the affected individuals carry heterozygous variants in genes (PKD1 and PKHD1, respectively) commonly associated with dominant and recessive polycystic kidney disease phenotypes." (PMID 41288877, 2025). "Polycystic kidney disease (PKD), a ciliopathy caused primarily by mutations in the Pkd1 and Pkd2 genes, disrupts renal structure and function, leading to progressive renal failure." (PMID 40507782, 2025).
polycystic kidney disease (continued). "Localization of Pkd1/2 to LECs has triggered the exploration of lymphatic vessel-related polycystic kidney disease." (PMID 39899153, 2025). "Polycystic kidney disease (PKD) was diagnosed in P15, P18, and P20, each carrying variants in PKD1, PKHD1, or with syndromic features suggestive of cystic pathologies." (PMID 41288877, 2025). "Previous studies have reported that polycystin 1 (PKD1) palmitoylation increases the protein level of PKD1 and promotes the occurrence of polycystic kidney disease." (PMID 39913299, 2025). "Studies have explored the genetics of early-onset polycystic kidney disease (PKD), focusing on dual variants in PKD1 and modifying genetic interactions." (PMID 40710847, 2025). "AGT and ACE variants were associated with renal tubular dysgenesis, while PKD1 and PKHD1 mutations indicated both dominant and recessive polycystic kidney disease." (PMID 41288877, 2025). "This case highlights the complexity of genetic interactions in polycystic kidney disease and suggests that fetal manifestations resembling ARPKD can occur in the context of ADPKD due to combined variants in the PKD1 gene." (PMID 40710847, 2025). "For example, larger gene deletion syndrome such as ‘TSC2 and PKD1 deletion’ has been described as a contiguous gene deletion syndrome, ‘Polycystic kidney disease, infantile severe, with tuberous sclerosis (OMIM: 600273)’, as PKD1 is in close proximity to TSC2." (PMID 38265426, 2024). "Currently, the PKD1 gene has been pinpointed as the primary cause of the ADPKD in cats, yet the presence of additional mutations potentially influencing feline polycystic kidney diseases remains an area of investigation." (PMID 38891834, 2024). "In fetuses with isolated renal anomalies, the highest detection rate of pathogenic variants was among fetuses with isolated polycystic kidney disease (29% PKHD1, PKHD1, PKD1, ETFA)." (PMID 37535131, 2024). "In ADPKD cohorts enriched for rapidly progressive disease, such as HALT Progression of Polycystic Kidney Disease (HALT-PKD) study and Consortium for Radiologic Imaging Study of PKD, PKD1 and PKD2 variants account for approximately 78% and 15% of cases." (PMID 37962562, 2024). "Polycystic kidney disease (PKD), which is most frequently associated with Autosomal Dominant PKD (ADPKD) due to PKD1 and PKD2 heterozygous variants, is emerging as a possible clinical manifestation in COL4A3-A5 patients." (PMID 38790225, 2024). "Polycystic kidney disease (PKD), a hallmark ciliopathy, is caused by mutations in the PKD1 and PKD2 genes which encode for the polycystin 1 (PC1), and 2- (PC2) proteins respectively." (PMID 36776558, 2023). "The expression levels of EGF and MCP1 were derived from microarray experiments on 13 renal cysts of different sizes, 5 minimally cystic tissue (MCT) from five PKD1 human polycystic kidneys and 3 normal renal cortical samples as control tissue." (PMID 36342644, 2023). "A study found that large mutational deletion of the TSC2 gene is correlated with the development of early-onset polycystic kidney disease in which the adjacent PKD1 gene was also affected by this deletion." (PMID 36422197, 2022). "ADPKD is caused primarily by mutations in PKD1 or PKD2, which encodes polycystin-1 (PC1) or polycystin-2 (PC2), respectively (polycystins or PCs collectively)." (PMID 35832738, 2022). "The polycystic kidney disease (PKD) genes PKD1 and PKD2 code for polycystin 1 (PC1) and polycystin 2 (PC2), respectively, and are known as the causal genes of ADPKD." (PMID 34980882, 2022). "For genetic workup, further polycystic kidney disease genes were analyzed, PKD1 and PKD2 in 12, HNF1B in 8, and DZIP1L and GANAB in 5 children each without detection of variants." (PMID 35812281, 2022). "A heterozygous likely pathogenic missense variant c.692T > C (p.Leu231Pro) was identified in exon 5 of PKD1, in a 40-year-old female who presented with polycystic kidney, arterial HTN, and liver cyst." (PMID 37543885, 2022).
polycystic kidney disease (continued). "In fact, neither activation nor repression of the Hedgehog signaling components (Smo, Gli2, and Gli3) influenced the progression of polycystic kidney disease in mouse Pkd1 models of developmental or adult-onset of ADPKD." (PMID 35832738, 2022). "Those small CNVs are the focus of MLPA analyses, which can be developed specifically for exons of genes known to be often affected by deletions/duplications, such as PKD1 or PKD2, causative of polycystic kidney disease." (PMID 34573409, 2021). "We excluded the AD polycystic kidney disease (ADPKD) patients with a clear family history in which modified PCR conditions were efficient for sequencing of the PKD1 gene." (PMID 34215756, 2021). "We demonstrate the utility of this approach in embryos with polycystic kidneys (pkd1 and pkd2) and craniofacial dysmorphia (six1)." (PMID 34739029, 2021). "The most common form of polycystic kidney disease (PKD) is inherited in an autosomal dominant (AD) manner and occurs due to mutations in PKD1 and PKD2, encoding polycystin 1 and 2, respectively." (PMID 33716764, 2021). "The three pathogenic variants were identified in the genes ACTA2 (multisystem smooth muscle dysfunction syndrome), PKHD1 (autosomal recessive form of polycystic kidney disease), and PKD1 (autosomal dominant polycystic kidney disease type 1)." (PMID 32779812, 2020). "As expected polycystic kidney disease was only found in those with TSC2 mutations because it is the result of a deletion stretching across the TSC2 and PKD1 genes on chromosme 16 (The “contiguous gene syndrome”)." (PMID 33041968, 2020). "Polycystic kidney disease due to mutations in PKD1 and PKD2, which produces polycystin 1 and 2, respectively, are the most common monogenic human kidney diseases, showing 100–1,000 fluid-filled renal cysts." (PMID 32226789, 2020). "In the Consortium of Radiologic Imaging Studies of Polycystic Kidney Disease (CRISP) cohort, 89.1% had either a PKD1 or PKD2 mutation." (PMID 31488014, 2019). "The proteins in the animal subclade 1 were annotated as PC-1 based on similarity to the human polycystic kidney disease (PKD1) genes." (PMID 31455637, 2019). "Compared with wild-type mice, Pkd1 miR Tg mice had significantly higher levels of Slc16a3 and Hk2 mRNA expression, indicating an increase in glycolytic activities in polycystic kidneys." (PMID 30585217, 2018). "Recent studies have reported intrinsic metabolic reprogramming in Pkd1 knock-out cells, implicating dysregulated cellular metabolism in the pathogenesis of polycystic kidney disease." (PMID 29426897, 2018). "We newly identified the regulation of miR-372-3p on PKD1/PKD2, indicating the possible association of miR-372-3p with polycystic kidney disease for the first time." (PMID 29941943, 2018). "The amino-acid sequences of s2, s2a and s2b resemble the polycystic kidney disease domain (PKD) that was first identified in the polycystic kidney disease protein PKD1 (The International Polycystic Kidney Disease Consortium, 1995 ▶)." (PMID 25760606, 2015). "Full-length PrtV protein contains 918 amino acids and consists of one M6 peptidase domain, a zinc- binding domain, and two C-terminal Polycystic Kidney Disease domains (PKD1 and PKD2)." (PMID 26222047, 2015). "The polycystic kidney disease gene product Polycystin-1 (PKD1) belongs to the only other protein family containing a GPS; in this protein context the GPS is also positioned close to a transmembrane domain." (PMID 22938866, 2012). "The selective deletion of Pkd1 in kidney by using Ksp-Cre, or more broadly Nestin-Cre, also leads to the formation of polycystic kidneys resembling human ADPKD." (PMID 23029375, 2012). "Regardless, unlike the embryonic lethality of global Pkd1 null mice, the conditional Pkd1 null mice are born alive and exhibit a 50% 6-week survival rate, thereby creating a new model to study polycystic kidney and pancreatic cystic disease postnatally." (PMID 23029375, 2012).
polycystic kidney disease (continued). "Some patients with TS carry a contiguous germline deletion that affects both the TSC2 gene and the adjacent gene, polycystic kidney disease type 1 (PKD1), resulting in a polycystic kidney phenotype that leads to early renal insufficiency." (PMID 20062701, 2009). "In 2–3% of patients with TSC, TSC2/PKD1 contiguous gene syndrome (CGS) is found as a distinct disease entity with clinical features typical of TSC combined with severe and early polycystic kidney disease, almost always associated with early progression to end-stage renal disease." (PMID 41227201, 2025). "Ultrasound sensitivity and specificity generally improved with age and were worse in PKD2 patients compared to PKD1 (lowest reported 31% and 88%, respectively, in polycystic kidney disease (PKD) 2 patients aged 5–14; highest 100% and 100%, respectively, in multiple gene/age categories)." (PMID 40697969, 2025). "The lymphatic deficiency appears before the development of kidney cysts, indicating that Pkd1 mutations directly disrupt lymphatic development through its role in LECs rather than indirectly through edema in polycystic kidneys." (PMID 39899153, 2025). "In addition, a contiguous gene deletion syndrome (deletion of both TSC2 and PKD1 genes, causing both TSC and polycystic kidney disease) was identified in 5 cases." (PMID 39726678, 2024). "The proportion of PKD1 or PKD2 pathogenic variants in patients without a positive family history of polycystic kidneys is low, and the presence of IFT140 pathogenic variants is significant." (PMID 39291187, 2024). "Notably, in one study utilizing the Han:SPRD (cy/+) rat model and an inducible PKD1 animal model of polycystic kidney disease (PKD), FGF-23 levels were increased, while tissue levels of Klotho did not exhibit any significant differences." (PMID 37985930, 2024). "However, numerous models have been proposed to elucidate the pathogenesis of ADPKD and the mechanisms by which mutations in the PKD1 and PKD2 genes lead to the development of polycystic kidneys." (PMID 38891834, 2024). "Next-generation sequencing (NGS)-based analysis of polycystic kidney disease (PKD)-associated genes in the proband revealed the presence of a pathogenic PKD2 variant and a likely pathogenic variant in PKD1, according to the American College of Medical Genetics and Genomics (ACMG) criteria." (PMID 37628640, 2023). "In the 2000s, polycystin-1 and polycystin-2 proteins (mechanosensory complex), encoded by the causative genes PKD1 and PKD2 of polycystic kidney disease (PKD), a genetic disorder, gained attention due to their specific presence in the primary cilia of renal tubular epithelial cells." (PMID 37900915, 2023). "Polycystic kidney disease (PKD) was ruled out by negative genetic testing of the causative genes PKD1 and PKD2." (PMID 37768732, 2023). "The PKD1 gene was identified over a quarter of a century ago." (PMID 36406261, 2022). "Although PKD1 gene mutation and aortic related complications were found in some patients, polycystic kidney did not appear in these patients." (PMID 33200202, 2020). "Children with TSC2/PKD1 CGS typically have severe polycystic kidney disease and may reach ESRD in young adulthood." (PMID 31118499, 2019). "Polycystic Kidney Disease (PKD), which is attributable to mutations in the PKD1 and PKD2 genes encoding polycystin‐1 (PC1) and polycystin‐2 (PC2) respectively, shares common cellular defects with cancer, such as uncontrolled cell proliferation, abnormal differentiation and increased apoptosis." (PMID 31251475, 2019). "In this paper, we applied fluid shear stress to study TGF-β signaling in renal epithelial cells with and without expression of the Pkd1-gene, encoding a mechano-sensor mutated in polycystic kidney disease." (PMID 28168444, 2017).